LYPD8 (LY6/PLAUR domain containing 8)
Description:
Secreted protein specifically required to prevent invasion of Gram-negative bacteria in the inner mucus layer of the colon epithelium, a portion of the large intestine which is free of commensal microbiota. Prevents invasion of flagellated microbiota by binding to the flagellum of bacteria, such as P.mirabilis, thereby inhibiting bacterial motility in the intestinal lumen. Segregation of intestinal bacteria and epithelial cells in the colon is required to preserve intestinal homeostasis.
Tractability: Antibody: its Gene Ontology location is reachable by antibodies, with high confidence; UniProt places it where antibodies can reach, with medium confidence; UniProt predicts a signal peptide or a membrane-spanning region.
Gene: Protein-coding gene on chromosome 1 (248,737,957 to 248,755,759, reverse strand). Ensembl gene ENSG00000259823.
Subcellular location: Cell membrane; Secreted
Pathways (Reactome):
Metabolism of proteins: Post-translational modification: synthesis of GPI-anchored proteins
Gene Ontology:
Biological process: defense response to Gram-negative bacterium
Cellular component: extracellular region; plasma membrane
Genetic constraint (gnomAD): Loss-of-function variants: 2 observed, 1.66 expected, observed/expected ratio (o/e) 1.2, 90% interval 0.41 to 1.9. That is too few expected variants to judge how well the gene tolerates losing a copy. Missense variants: 85 observed, 98.95 expected, observed/expected ratio (o/e) 0.86, 90% interval 0.72 to 1.03. Synonymous variants: 39 observed, 43.41 expected, observed/expected ratio (o/e) 0.9, 90% interval 0.69 to 1.17.
Homologues: Orthologues: chimpanzee LYPD8 (99% identical), macaque LYPD8 (87% identical), pig LYPD8 (55% identical), dog LYPD8 (52% identical), rat Lypd8 (42% identical), mouse Lypd8 (41% identical), zebrafish ly6m3 (20% identical), zebrafish ly6m6 (19% identical), zebrafish ly6m7 (19% identical), zebrafish ly6m2 (18% identical), zebrafish ly6m4 (18% identical), zebrafish si:ch211-134a4.6 (18% identical), and 4 more. Paralogues in human: PINLYP (16% identical).
Diseases named in the same sentence as LYPD8 in open-access papers:
LYPD8 is named in the same sentence as 10 diseases in open-access papers, as found by Europe PMC text mining. Sharing a sentence is not in itself a finding about the gene and the disease. The quoted sentences say what the papers report.
colitis (4 papers, 2018 to 2022). Inflammation of the colon. "The abundance of Proteus in faeces and colon tissues is also significantly higher in Lypd8-/- mice, which are susceptible to DSS-induced colitis, than in WT mice." (PMID 34373435, 2021). "LYPD8 levels are significantly decreased in colitis patients, and supplementation of LYPD8 proteins might maintain colonic homeostasis in colitis patients by inhibiting the motility of pathogenic bacteria, such as γ-proteobacteria." (PMID 35893911, 2022).
colon cancer (2 papers, 2021 to 2023). "Association between IL‐6/TNF‐α and the expression of LYPD8 in colonic tumor tissue, precancerous tissue and normal tissue at different stages." (PMID 33882644, 2021). "**P<0.01, LYPD8 mRNA expression of normal tissue, precancerous tissue vs. colonic tumor tissue in stage II and IV tissues." (PMID 33882644, 2021). "(C) Gene expression of LYPD8 in stage II and IV colonic tumor tissue and precancerous tissue." (PMID 33882644, 2021).
Insulin resistance (1 paper, 2022). Increased resistance towards insulin, that is, diminished effectiveness of insulin in reducing blood glucose levels. "Regardless of insulin resistance, the two groups of women with morbid obesity showed upregulation of LYPD8 and downregulation of a greater number of genes, such as REG1B, GKN2, LPL, PNLIPRP2, FKBP5, and CD86, that are related to responses to bacterial stimuli and antimicrobial activity." (PMID 35625760, 2022).
intestinal inflammation (1 paper, 2021). "It has been demonstrated that Lypd8 could promote the segregation of flagellated microbiota and colonic epithelia by using DSS-induced intestinal inflammation in Lypd8(-/-) mice." (PMID 33819198, 2021).
ulcerative colitis (1 paper, 2017). An inflammatory bowel disease involving the mucosal surface of the large intestine and rectum. "In addition, it was found that human LYPD8 (hLYPD8) is expressed in the colonic epithelia and expression of hLYPD8 is reduced in some ulcerative colitis patients." (PMID 29259722, 2017).
infection (2 papers, 2022 to 2024). The state of being infected such as from the introduction of a foreign agent such as serum, vaccine, antigenic substance or organism. "However, whether LYPD8 prevents infection with E. coli F17 still needs to be determined." (PMID 35498757, 2022).
tumor (2 papers, 2019 to 2023). "In the present study, LYPD8 was underexpressed in the tumor tissues and was associated with poor prognosis." (PMID 31024853, 2019).
LYPD8 also shares sentences with these, for which no sentence is quoted: brain tumors (1 paper); colorectal cancer (1); morbid obesity (1).